PLK1 (polo like kinase 1)
Diseases named in the same sentence as PLK1 in open-access papers (continued):
Sharing a sentence is not in itself a finding about the gene and the disease.
cancer (continued). "The relation between dysregulated PLK1 and chromosomal instability (CIN) makes it an attractive target for cancer therapy." (PMID 33066048, 2020). "The accumulation of APC targeted mitotic kinases like PLK1, MPS1, and Aurora A/B in cancer has led to efforts to target these molecules for anticancer therapy." (PMID 32805721, 2020). "Several pathways/mechanisms such as COX-2, Nrf2, poly-ADP-ribosylation, Hedgehog, Wnt, Plk1, STAT3, NF-κB, PI3 kinase, or epigenetic modulations are implied in the modulation of cancer proliferation." (PMID 33375383, 2020). "Our analysis revealed that the expression patterns of AURKB, CCNB1, PLK1, and USP7 were all higher in tumor tissues than in normal tissues, although their basal levels were different in each cancer." (PMID 33207738, 2020). "To compare the functional maps with their corresponding protein structures, we highlighted those critical residues identified from PASTMUS on the surface diagram of three cancer drug targets (PSMB5, PLK1, and HPRT1)." (PMID 31842968, 2019). "To further substantiate the clinical relevance of the B-Myb/FoxM1/Cdk/Plk1 axis we applied PRECOG, a pan-cancer resource of expression signatures that correlates cancer gene expression and clinical prognosis data through calculation of meta-z-scores." (PMID 30321399, 2019). "For example, we observe that PLK1, CCNB1/2, CCNA2, AURKB and BUB1B are shared across 6–9 cancer types and physically interact with several deregulated neighbouring genes in our activated modules." (PMID 31396397, 2019). "In cancer cell lines and xenograft models including fusion positive RMS it has been noted that reduction of PLK1 expression or its inhibition leads to mitotic arrest which can lead to apoptosis." (PMID 31824851, 2019). "Both USP7 and PLK1 have been considered bona fide cancer targets, and USP7 or PLK1 inhibitors have been developed to experimentally treat different cancer types or to re-sensitize cancer cells to overcome therapeutic resistance." (PMID 31730000, 2019). "In summary, results here demonstrate that PLK1 and FOXM1 are participants in the hyperplastic phenotype of PAH HPASMC and support the cancer paradigm for PAH vascular cells proposed by Rai and coworkers." (PMID 31437238, 2019). "The role of AURKA, PLK1 and FOXM1 in cancer pathogenesis and progression arises from their interaction with β-catenin, which is a central signal for normal and CML stem cells." (PMID 31122263, 2019). "The levels of expression of PLK1 in pediatric cancers and RMS are comparable to high levels seen in many adult cancers and are even higher in pediatric cancer cell lines, including those representing RMS." (PMID 31824851, 2019). "By acting on multiple targets including PLK1, EGFR, and ER, genistein is a promising compound for cancer prevention and treatment." (PMID 31100782, 2019). "In particular, the four overlap non-cancer genes (CDK1, CDK2, PLK1 and WEE1), which were validated by the three data resources, were all known anticancer drug targets and clinical trial targets." (PMID 29855504, 2018). "The GDSC data involved the drug sensitivity (IC50) of cancer cells to hundreds of compounds, of which GW84368 and BI-2536 target PLK1." (PMID 30631355, 2018). "Expression levels of PLK1 and HRAS in HCC patients were analyzed using the OncomineTM human cancer microarray database." (PMID 29423069, 2018). "We selected several known important proteins in cancer biology, including STAT3, CDC25C, and PLK1, and validated RPPA data by western blotting." (PMID 30221473, 2018). "Otherwise, Polo-like kinase 1 (PLK1) plays a key role in mitotic progression and cell-cycle control, which is confirmed to be one of the potential drug targets for cancer therapy." (PMID 30213130, 2018).
cancer (continued). "Target gene candidates in cancer therapy are mainly involved in oncogenes, angiogenesis and proliferation, like PLK1, EphA2, RRM2, KRAS, PKN3 and VEGF, which have been tested as target genes in early-phase clinical trials for RNAi-based cancer therapies." (PMID 30065155, 2018). "PLK1 is often overexpressed in a broad spectrum of cancers, including GBM (proteinatlas.org), and high PLK1 expression levels correlate with poor prognosis." (PMID 29535822, 2018). "PLK1 is the best-described PLK protein, and is frequently used as a tumor marker, as high PLK1 expression correlates with poor prognosis in cancer." (PMID 28102733, 2017). "PDK1 triggers the phosphorylation of PLK1, which is also upregulated in many cancers, and the latter interacts with MYC, phosphorylates it and results in its accumulation in cancer cells." (PMID 29064423, 2017). "Importantly, PLK1 could act as an oncogene by promoting proliferation in human cancer." (PMID 27862966, 2017). "Here, the effect of Plk1 inhibition on the MEK-ERK-RSK1 signaling pathway in both MKN45 and MKN74 CSC-like and cancer cells was examined." (PMID 28430578, 2017). "The control of kinetochore-microtubule attachment is governed by an extensive network of different proteins, including PLK1, the Aurora A and B kinases, and cyclin-CDK complexes, which have been reported dysregulated in cancer cells." (PMID 28445142, 2017). "Inhibition of Plk1 induced overall suppression of the MEK-ERK-RSK1 signaling pathway in the CSC-like cells, but over-activated ERK and RSK1 in the cancer cells." (PMID 28430578, 2017). "Taken together, our data demonstrate that Plk1, a critical cell cycle regulator, promotes oxidative PPP and biosynthesis in cancer cells." (PMID 29138396, 2017). "First, Aurora A activates Plk1 to enable successful sphere formation by the CSC-like cells and proliferation of the cancer cells." (PMID 28430578, 2017). "To confirm that treatment with BI 2536 and BI 6727 inhibits activation of Plk1 in MKN45 CSC-like cells and cancer cells, we measured the phosphorylation of Myelin transcription factor 1 (Myt1), a Plk1 substrate." (PMID 28430578, 2017). "Recently, specific inhibitors of protein kinases in Plk1 and RSK1 signaling pathways have been used to study cell cycle regulation, including some which are expected to be clinically used as anti-cancer agents." (PMID 28430578, 2017). "Western blot analysis showed that Plk1 activity was successfully inhibited in MKN45 CSC-like and cancer cells after BI 2536 and BI 6727 treatment." (PMID 28430578, 2017). "Based on our results, CSCs can enter the quiescent state in response to unsuitable environments via the Plk1 and RSK1 signaling pathway, but cancer cells cannot." (PMID 28430578, 2017). "Nonetheless, each of these screens identified multiple mitotic kinases as essential in various cancer cell lines, including Aurora B, BubR1, CDK1, and Plk1." (PMID 28337968, 2017). "We identified consistently upregulated genes (such as E2F1, EZH2, FOXM1, MYBL2, PLK1, TTK, AURKA/B and BUB1) and consistently downregulated genes (such as SCARA5, MYOM1, NKAPL, PEG3, USP2, SLC5A7 and HMGCLL1) across various cancers." (PMID 28427185, 2017). "Our findings highlight the importance of carefully monitoring PLK1-, MTOR-, and autophagy- activities in clinical studies, to identify leads for cancer therapy design." (PMID 28102733, 2017). "Our study demonstrated the clinical feasibility of exploring a synthetic lethal regimen of the combined inhibition of PLK1 and ROCK to defeat KRAS-mutant cancer through a mechanism that involves activation of tumor suppressor P21." (PMID 27793187, 2016).
cancer (continued). "We also showed that inhibitors of polo-like kinase 1 (PLK1) can upregulate miR-200c/141 cluster, which indirectly results in downregulation of BMI1 and cancer stem cell phenotype." (PMID 27105531, 2016). "Little is known about PPIC in cancer, however PPIA and another PPIase PIN1 have been shown to interact with key growth and signalling proteins including cyclin D1, CDK10, cdc27, and PLK1, with diverse downstream effects on MAPK signalling." (PMID 27852308, 2016). "Our results show that dual inhibition of polo-like kinase 1 and RhoA/Rho kinase (ROCK) leads to the synergistic effects in KRAS-mutant cancers." (PMID 27193833, 2016). "Next, we extensively investigated the effects of combined inhibition of the PLK1 and Rho signalling pathways on KRAS-mutant cancers in vitro and in vivo." (PMID 27193833, 2016). "On the basis of the broad efficacy of combined PLK1 and ROCK inhibition against KRAS-mutant cells in vitro, we assessed the therapeutic efficacy of this combination in a series of preclinical cancer models in vivo." (PMID 27193833, 2016). "Our study revealed a preclinical rationale for exploring a synthetic lethal regimen that combined the inhibition of PLK1 and Rho signalling to conquer KRAS-mutant cancer." (PMID 27193833, 2016). "The essentiality of PLK-1 for normal cell cycle progression and mitosis has raised lingering questions regarding the targeting value of PLK-1 in cancer chemotherapy." (PMID 26557691, 2015). "RO3280 inhibited the enzymatic activity of PLK-1 with an IC50 of 3 nM and EC50 of 6.0–82 nM against several cancer cell lines in vitro." (PMID 26557691, 2015). "The PBD domain is identified as a chemotherapeutic target for cancer based on its implication in PBD-dependent substrate targeting and subcellular localization of PLK-1." (PMID 26557691, 2015). "Our observation is supported by the data from other studies of Plk1 inhibitors, such as BI 2536 and the PBD inhibitor purpurogallin (PPG), impacting both cancer cells as well as normal cells with a comparable sensitivity." (PMID 23948487, 2013). "Therefore, NFBD1 might be exposed to PLK1-mediated hyperphosphorylation in cancer cells." (PMID 24349352, 2013). "Although the beta-carboline compounds can inhibit the kinase activity of PLK1, PLK2 and PLK3, it is likely that the inhibition of PLK1 contributes to toxicity of these compounds to cancer cells." (PMID 23056340, 2012). "Clinical trials in cancer patients are currently underway to evaluate the effects of PARP and Plk1 inhibitors." (PMID 22325354, 2012). "We selected the overlapped genes-PLK1, MCM2, MCM3, MCM7, MCM10 (ranked 13 by NGP-NR in NSCLC patient datasets) and SKP2 to investigate their functions in cancer." (PMID 22838965, 2012). "Here we used RNAi screening to look for sensitizers to the candidate cancer drug GSK461364A, a potent inhibitor of polo-like kinase 1 (PLK1)." (PMID 22248814, 2011). "As PLK-1 is overexpressed in other various cancers, PLK-1 overexpression is a prognostic biomarker for cancer patients." (PMID 21884621, 2011). "PLK-1 mRNA levels were elevated in NSCLC tissues and this transcript levels were correlated with the survivals of cancer patients." (PMID 21884621, 2011).
cancer (continued). "The most dramatic and uniform changes we observed were in a set of about 30 genes that are characterized as a "cancer proliferation cluster," which includes genes expressed during mitosis (CDC2, CDC25, MCM2, PLK1) and following DNA damage." (PMID 17233903, 2007). "These and other studies have shown that a common set of genes is consistently overexpressed in most cancers, including many cell cycle regulated genes and genes required for mitosis (e.g. MKI67, PCNA, BIRC5, MYBL2, TOP2A, PLK1, MCM2-MCM6, CDC20)." (PMID 17233903, 2007). "PLK1 has emerged as a key regulator of multiple transcription factors, including STAT3, c-Myc, FOXM1, and β-catenin, positioning it as a promising combinatorial therapeutic target for disrupting oncogenic signaling networks in cancer." (PMID 41539998, 2026). "Moreover, based on the blue module genes screened by WGCNA and existing researches, AURKA, TPX2, CHEK1, and PLK1 were found to be highly related to NCAPH and were involved in the regulation of PI3K/AKT pathway in cancer." (PMID 38587786, 2025). "Polo-like kinase 1 (PLK1) is a well-known regulator of the cell cycle and participates in multiple mitotic processes, thus gaining considerable interest as a novel target in cancer treatment." (PMID 41284701, 2025). "Inhibition of PLK1 expression could resensitize cancer cells and improve response to therapy even in difficult to treat KRAS mutant cancers." (PMID 40615690, 2025). "Plk1 and its downstream targets, including mitotic spindle positioning (MISP), RhoGDI1, and FoxM1, regulate proliferative and invasive capabilities through epithelial-mesenchymal transition (EMT) transition in cancer cells." (PMID 40166466, 2025). "Consistent with this idea, the viability of PLK1-overexpressing cancer cells in the absence of IGF2BP2 activity was partially rescued by supplying exogenous ATP in our experiments." (PMID 40347943, 2025). "Given the predominant immunosuppressive functions of PLK1 in LUAD and other cancer types, treatment focuses on targeting PLK1 may decelerate tumor growth by boosting immune response in TME." (PMID 38885192, 2024). "Moreover, we examined the protein expression levels of the four ARGs (PLK1, SLC2A1, ANGPTL4, CDKN3) in cancer tissues and para-cancer tissues from clinical LUAD patients." (PMID 38345559, 2024). "Besides, the expression level of CDK1, CCNA2, CHEK1, KIF11, PLK1 and TTK was significantly elevated with cancer progression in LUAD." (PMID 38783288, 2024). "In addition, the expression level of CDK1, CHEK1, KIF11, PLK1 and TTK was significantly elevated with cancer progression in LUAD." (PMID 38783288, 2024). "Targeting of either TTK or PLK1 has been clinically evaluated in cancer patients; however, dual inhibitors have not yet been pursued." (PMID 39184047, 2024). "Although there is no direct homolog in humans, POLO-LIKE KINASE 1 (PLK1) is a related gene which shares functional similarities, the over-expression of which is associated with various kinds of cancer." (PMID 38279283, 2024). "Last but not least, all the regulatory enzymes discovered in this study, including USP34, Pin1, Plk1, CDK1 and Ubc9, could be effective drug targets for combination therapies to treat GBMs and potentially other malignant tumors." (PMID 38167292, 2024). "In addition, elevation of PLK1 attenuates the expression of class II major histocompatibility complex (MHC-II) in professional antigen presentation cells and cancer cells, leading to impaired antigen presentation and anti-tumor immunity." (PMID 38885192, 2024).
cancer (continued). "Although the functional significance of PLK-1 in carcinogenesis and malignant progression is not yet fully understood, its inhibition has been shown to result in growth cessation or apoptosis of cancer cells in previous reports." (PMID 39857637, 2024). "Gene expression analysis suggests that its mechanism of action may involve downregulation of cancer-related genes such as AKT1, BCL2L1, CCND1, CDK4, PLK1, and RHOA." (PMID 38751791, 2024). "During mitosis, PLK1 interacts and phosphorylates the N-terminus of SPAG5 (also known as astrin), which has been reported to upregulate the PI3K/AKT pathway in cancer cells in vitro through the centrosome protein CEP55." (PMID 38534420, 2024). "These siRNA-target genes are mainly those that promote cell differentiation and proliferation and inhibit apoptosis, which are overexpressed in cancer cells, such as Bcl-2, survivin, epidermal growth factor receptor (EGFR), Janus kinase 1 (JAK1), and polo-like kinase 1 (PLK1)." (PMID 39407665, 2024). "In addition, Polo-like kinase 1 (PLK1), which has been recognized among the possible therapeutic targets for cancer treatment, is essential for mitotic progression and cell-cycle regulation." (PMID 38129839, 2023). "Similarly, another study has shown that exosomes loaded with PLK-1 siRNAs promoted bladder cell apoptosis by silencing the expression of polo-like kinase 1 (PLK-1), a major driver of cancer cell growth and proliferation." (PMID 36766698, 2023). "On account of its critical participation in mitotic and non-mitotic processes, PLK1 is established as a favorable therapeutic target for cancer therapy." (PMID 38104151, 2023). "The results suggest that the synergistic effect of the cell-cycle-related genes UBE2C, PLK1, and BIRC5 may promote the development of pan-cancer by affecting cell metabolism." (PMID 37958642, 2023). "Moreover, we further validated that PLK1-induced UHRF1 phosphorylation and protein stability is required for the silencing of TSGs and sustaining cell viability for cancer cells." (PMID 37788997, 2023). "Thus, our results provide the basic evidence that HMGA1 and FOXM1 cooperatively accelerate cell cycle progression by up-regulating PLK1 and CCNB1 to promote cancer cell proliferation." (PMID 37240870, 2023). "Our study deciphers that the axis of ST8SIA6-AS1/PLK1/c-Myc confers both intrinsic and acquired resistance to KRASG12Ci and represents a promising therapeutic target for combination strategies with KRASG12Ci in the treatment of KRASG12C-mutant cancers." (PMID 38104151, 2023). "Our findings demonstrate that the pharmacological co-inhibition of PLK1 and ACLY significantly suppresses pan-cancer cell proliferation compared to single-agent treatment and that this combination downregulated UBE2C mRNA and protein expression, which revealed a novel potential molecular mechanism." (PMID 37958642, 2023). "The results showed that the knockdown or silencing of DAP3 and PLK1 genes could inhibit the growth of most HCC cells and many other cancer cells." (PMID 37415742, 2023). "The suppression of PLK1 can induce DDR and cell apoptosis in cancer cell lines." (PMID 38037110, 2023). "By analyzing the clinical significance and prognosis of G2/M related genes (PLK1, CDK1, CCNB1, and CCNB2) in various cancer tissues, we found that they were up-regulated in most cancer types, and their down-regulation showed better overall survival rates in cancer patients." (PMID 37007025, 2023). "Not surprisingly, studies show that various cancer cells, but not their isogenic normal cells, are addicted to Plk1 overexpression for their viability (3, –5)." (PMID 37603740, 2023). "Notably, 40 DERIs were found to be specifically detected in the nuclear fraction, and many of these were from known cancer‐related genes, including AGRN, DKC1, PKMYT1, PLK1, and MARS1." (PMID 36461702, 2023).